IL13 (interleukin 13)
Diseases named in the same sentence as IL13 in open-access papers (continued):
Sharing a sentence is not in itself a finding about the gene and the disease.
fibrosis (62 papers, 2008 to 2026). the formation of excess fibrous connective tissue in an organ or tissue in a reparative or reactive process. "As mentioned, IL-13 is associated with fibrosis, diarrhea, and perianal inflammation in a cholestasis model, and IL13 knockout improves liver function and liver structure, as well as the enteric barrier in mice." (PMID 37629063, 2023). "In BA patients, increased levels of IL-7, eotaxin, IP-10, and IL-13 were significantly associated with unfavorable outcomes including jaundice, fibrosis, and portal hypertension." (PMID 35452452, 2022). "In our study we found decrease of DC-SIGN expression on liver endothelial cells in patients with advanced fibrosis that is presumably associated with the decrease of IL-4 and IL-13 production." (PMID 31318916, 2019). "Conversely, data from parasitic fibrosis models in liver have demonstrated complete abrogation of fibrosis in IL-13 deficient mice despite undiminished TGF-β production." (PMID 28004808, 2016). "Enhance the secretion of IL-5 and IL-13 which can cause pulmonary inflammation and fibrosis." (PMID 34707601, 2021). "Only IL-13 was significantly lower in MASLD with fibrosis patients, when compared to both unmatched and matched MASLD patients without fibrosis (β= −0.24; 95%CI [−0.41,-0.085])." (PMID 38235661, 2024). "IL-13 has also been shown to mediate the processes of tissue fibrosis via the transforming growth factor-β-dependent and -independent pathways." (PMID 36295022, 2022). "We did not observe a significant difference in correlation of the frequency of CD4+T cells expressing TGF-β with CD4+ IL-4+ and CD4+IL-13+ T cells in the group of individuals with periportal fibrosis." (PMID 33692784, 2021). "Fibrosis in chronic TNBS treated mice seemed driven by IL-13 via TGF-β1 production, and IL-13 blocking resulted in the prevention of intestinal fibrosis." (PMID 34737752, 2021). "IL-4/IL-13 double KO mice showed reduced liver granulomas and improved fibrosis along with IL-13 KO mice." (PMID 34281269, 2021). "Most experimental studies demonstrate the role of Th2 cytokines (IL-4, IL-5, and IL-13) in the formation of granuloma and of the Th17 response in advanced fibrosis." (PMID 34970264, 2021). "Stimulation with the Th2 cytokines IL-4 and IL-13 significantly increases hCLCA1 protein expression in mucosal tissue explants from the upper airways of fibrosis patients." (PMID 33066398, 2020). "The clinical impact of IL-13 and downstream signaling events in chronic liver diseases of different etiologies and fibrosis were recently summarized." (PMID 32846954, 2020). "More interestingly, a recent report found that co-inhibition of IL-13 and transforming growth factor-β (TGF-β) signaling attenuate the fibrotic machinery more completely than inhibiting TGF-β alone in NAFLD-associated fibrosis." (PMID 32283835, 2020). "In relation to cytokine levels in F0 group, statistically significant decrease in group of patients with fibrosis (F1, F3) was recorded for IFNγ (p = 0.039), IL-2 (p = 0.033), IL-17 (p = 0.039) and IL-13 (p = 0.047)." (PMID 31318916, 2019). "IL-13 is a key mediator of tissue fibrosis and a potent stimulator and activator of TGF-β, as well as a direct stimulus for collagen production." (PMID 29145453, 2017). "IL-13 is a pro-fibrotic cytokine that drives tissue fibrosis in this disease and in vitro experiments revealed that IL-33 increases the proportion of IL-13-producing Tregs in cultures of skin biopsies from healthy controls." (PMID 25741338, 2015). "In one study, treatment with paeoniflorin reduced the size of egg granuloma, fibrosis scores, IL-13 serum concentration, and hydroxyproline content in the liver of mice infected with S. japonicum." (PMID 25897319, 2015). "Alternatively, IL-13 is recognized as a Th2 cytokine that can contribute to sub-epithelial fibrosis and a pro-fibrotic cytokine in lung diseases." (PMID 25472740, 2014).
fibrosis (continued). "It is interesting to note that the IL-13 lung-fibrosis model is dependent on TGFβ1, whereas other IL-13-dependent models of fibrosis (e.g. S. mansoni) are not." (PMID 24713275, 2014). "Fibrosis severity correlates with IL-13 levels and is reduced by expression of the IL-13 decoy receptor, IL-13Rα2, or by neutralising antibodies for IL-13 in a murine model of S. mansoni." (PMID 23840855, 2013). "More recently, LIGHT has been implicated in induction of airway fibrosis and smooth muscle hyperplasia via TGF-ß and IL-13 production in an allergic animal model." (PMID 23844029, 2013). "Interestingly, an increase in IL-13 and TGF1β-producing cells was also detected in BM biopsies of patients diagnosed with myeloid neoplasm with fibrosis (PMF, post-ET MF, and myelodysplastic syndrome with BM fibrosis)." (PMID 37760903, 2023). "Conversely, the IL-13/IL-4/IL-Rα/IL-13Rα1 axis blockage by induced IL-4Rα deficiency in the shorter latency disease model (MPLW515L mice) prolonged survival and reduced BM fibrosis, WBC counts, spleen and liver size, and BM MK numbers." (PMID 37760903, 2023). "Moreover, IL-13 is a pivotal inducer of bronchial sub-epithelial fibrosis due to fibroblast proliferation and collagen production, and these effects are at least in part mediated by IL-13-dependent activation of transforming growth factor-β1 (TGF-β1)." (PMID 35350765, 2022). "They participated in autoimmune and tissue fibrosis by producing IL-4 and IL-13." (PMID 36408259, 2022). "It was also shown that overexpression of IL-10 aggravates silica-induced pulmonary inflammation and fibrosis in mice, which might relate to the promotion of Th2-type cytokine reaction and increased expression of IL-4 and IL-13." (PMID 29673394, 2018). "IL-4 and IL-13 have a key role in the development of pneumonitis and fibrosis." (PMID 30607342, 2018). "Under an interventional approach, LASSBio-448 reversed ongoing lung eosinophilic infiltration, mucus exacerbation, peribronchiolar fibrosis and AHR by allergen provocation, in a mechanism clearly associated with blockade of pro-inflammatory mediators such as IL-4, IL-5, IL-13 and eotaxin-2." (PMID 27695125, 2016). "Infection by S. mansoni eggs results in a granuloma-associated fibrosis that, in contrast to injury-induced fibrosis, appears to be driven by the Th2 cytokine IL-13, with little-to-no role for the traditional fibrotic stimulant TGFβ1." (PMID 24713275, 2014). "Our data established a novel link among IL-13, tTG, and liver granuloma and fibrosis." (PMID 25110399, 2014). "In the bleomycin-induced fibrosis model, IL-13 was elevated as expected." (PMID 25551570, 2014). "Additionally, IL-4 and IL-13 participate in fibrosis of skin and internal organs." (PMID 36985596, 2023). "Moreover, infected KO rats displayed a marked decrease in the levels of both Th1- (IFN-γ) and Th2-associated cytokines (IL-4, IL-5) at all time points post-infection, except with IL-2 and IL-13, both of which play an important role in granuloma and fibrosis development." (PMID 35584107, 2022). "Interestingly, IL-13 modulates TGFβ1 signalling during airway fibrosis, and alcohol’s priming effect for increased IL-13 signalling may play a role in lung transplantation related injury." (PMID 23547562, 2013). "We first evaluated the frequency of T CD4+ lymphocytes expressing IL-4, IL-5, and IL-13 after stimulation with SEA, since these cytokines are the main molecules involved in the pathogenesis of periportal fibrosis related to Schistosoma mansoni infection." (PMID 33692784, 2021). "This highlights the important role played by IL-13/STAT6 axis in cancer development in NASH, in both lower and advanced fibrosis grades patients." (PMID 32283835, 2020). "Compared with BA patients without fibrosis, plasma levels of 3 anti-inflammatory cytokines including IL-4 (P = 0.026), IL-10 (P = 0.048), and IL-13 (P<0.001) were significantly increased in those with fibrosis." (PMID 35452452, 2022).
fibrosis (continued). "In this study, the group with fibrosis showed a higher frequency of CD4+ T lymphocytes expressing IL-13 when compared to individuals without fibrosis, as well as higher levels of this cytokine in the supernatant of PBMCs cultures stimulated with SEA." (PMID 33692784, 2021). "In this analysis, IL-10 differed significantly between females and males in the nonfibrotic group whereas IL-13 was high in males with fibrosis compared to females in the same group." (PMID 29610679, 2018). "We found, however, higher levels of serum IL-13 in the group of individuals without periportal fibrosis compared to patients with severe fibrosis." (PMID 23320145, 2012). "Interestingly, serum IL‐13 was decreased in severe fibrosis patients compared to individuals without fibrosis, but still elevated in men with fibrosis compared with women." (PMID 41546136, 2026). "From Malaysian hepatitis B cohorts, we know that the serum concentrations of IL-13 were positively correlated with the controlled attenuation parameter (CAP), an ultrasound-based technique for measuring hepatic fat content independently from the presence of fibrosis." (PMID 37629063, 2023). "However, the IL-10/IL-13 ratio was higher in the group without fibrosis, compared to the PPF/PF group (p <0.01)." (PMID 33692784, 2021). "Compared to CD4+ T cells, ILC2s produce high levels of IL-13, but not IL-4, while IL-25 triggers IL-13+ ILC2-mediated fibrosis in the lung after injection of Schistosoma eggs." (PMID 32922381, 2020). "During CHC treatment, patients with SLD had distinct cytokine and growth factor kinetics, with SLD being the main source of variation in several cytokines (IL-5, IL-9, IL-10, IL-13, IL-17A, IL-22) and growth factors (EGF, VEGF and ANG), and it seems this was independent of fibrosis stage." (PMID 39200991, 2024). "Higher levels of IL-13 and MIP-1α in individuals without periportal fibrosis were also documented." (PMID 23320145, 2012).
glioblastoma (58 papers, 2010 to 2026). The most malignant astrocytic tumor (WHO grade IV). "The cytokines IL-1Ra, IL-13, and IFNγ showed poor diagnostic usefulness for prognosis in glioblastoma patients even though their concentrations changed significantly." (PMID 38003396, 2023). "Amphiphilic Hydrochalarones were used as a platform for developing novel glioblastoma-targeting theranostics in which the diagnostic agent is enclosed within glioblastoma-targeting IL-13 liposomes that can deliver a therapeutic payload of doxorubicin that was encapsulated within the lipid bilayer." (PMID 24300561, 2013). "This led to development of a possible targeted treatment, IL13 conjugated to pseudomonas exotoxin (IL13-PE), which potently and specifically killed glioblastoma (GBM) cells." (PMID 40663259, 2025). "Intracranial administration of CAR-T cells targeting IL13Rα2, a monomeric high-affinity receptor for IL-13 found to be overexpressed in glioblastomas, improves T-cell persistence and antitumor efficacy against glioblastoma." (PMID 37420216, 2023). "Although IL-13 hardly emerged as a good biomarker in glioblastoma (AUC = 0.536, specificity 85%, sensitivity 38%, RR = 0.459, 95%CI 0.213–0.888), its diagnostics usefulness increased in NLR + IL-13 model to AUC = 0.830 and classifier accuracy >80%." (PMID 38003396, 2023). "For example, IL-13 conjugated with Pseudomonas exotoxin subunits (IL-13-PE) has been developed for glioblastoma therapy." (PMID 37345109, 2023). "For instance, IL13-E13Y-containing CARs showed a 50-fold higher affinity for IL13Ra2 and a 5-fold lower affinity for IL13Ra1 than wild-type IL13 in glioblastoma multiform models." (PMID 37108788, 2023). "Conclusively, it is derived that removal of IL-13 from the system would be a factor toward escape of apoptosis from glioblastoma cells." (PMID 35612318, 2022). "Data from phase-I clinical trial have demonstrated that three glioblastoma patients were subjected to collection of peripheral mononuclear cells that were further engineered to CD8+ cytotoxic T lymphocytes expressing IL13-zetakine." (PMID 35612318, 2022). "IL13RA2, one of the high-affinity membrane receptors of IL-13, is highly expressed in tumors, such as liver cancer, glioblastoma, colon cancer, and pancreatic cancer." (PMID 35770008, 2022). "In comparison to normal brain tissues, glioblastoma is overexpressed with certain type of cytokine receptors known as IL13Rα2 that exhibit high affinity for IL-13." (PMID 35612318, 2022). "MV was also designed to express interleukin-13 (IL-13) directed to the IL-13Rα2 receptor on glioblastoma (GBM) cells, or the single-chain antibody versus the vIII variant of epidermal growth factor receptor (EGFRvIII)." (PMID 34439595, 2021). "IL-13 received attention as an important cytokine since a significant overexpression of the IL-13-receptor-α (IL-13Rα) has been detected in glioblastoma." (PMID 34654395, 2021). "Interleukin-13 receptor alpha-2 (IL-13Rα2), the high-affinity receptor for IL-13, is frequently overexpressed in the majority of glioblastoma multiforme (GBM) tumors in comparison to normal healthy brain tissue." (PMID 35011583, 2021). "Other, less well-known substances included the glutamate receptor inhibitor talampanel and cintredekin besudotox, an IL13 conjugated toxin, specifically targeting glioblastoma." (PMID 34234357, 2021). "Clinical application of this technology is reported for HSV1-tk-transduced CAR-T cells engineered to express an interleukin-13 (IL-13) zetakine, which targets IL-13 receptor alpha 2-expressing glioblastoma." (PMID 32582173, 2020). "Next, we investigated the effect of the D1 peptide on the downstream IL-13/ IL13Rα2 signalling in colorectal and glioblastoma cell lines." (PMID 30318506, 2018). "T98G glioblastoma cells were transfected with a plasmid encoding T-antigen and were treated with IL-2, Rantes, IFN-γ, IL-1β, IL-13 and MCP1 at 12, 24, and 36hrs post-transfection." (PMID 26061652, 2015).
glioblastoma (continued). "IL-13-PE was used in a Phase 3 clinical study to treat patients with glioblastoma multiforme, another cancer type wherein IL-13Rα2 is overexpressed in the majority of tumor cells." (PMID 23421960, 2013). "Observations from this current work lead us to infer that IL13-zetakine CTLs can efficiently target and kill IL13Rα2pos glioblastoma cells expressing mesenchymal gene signature phenotypes." (PMID 24204956, 2013). "Pilot clinical trials have been initiated to evaluate the feasibility and safety of local-regional delivery of autologous IL13-zetakine redirected CTL clones in patients with recurrent glioblastoma (GBM)." (PMID 22496835, 2012). "IRE1α-XBP1 stimulates interleukin-5 (IL-5) and interleukin-13 (IL-13), mediating a proliferative drive; however, these pro-inflammatory cytokines can also be counterproductive, promoting lung metastasis and glioblastoma invasion." (PMID 41301006, 2025). "Glioblastoma, an example of head and neck cancer, showed similar IL13/CART cell antigen escape." (PMID 36765809, 2023). "IL13Rα2 is an attractive target due to its overexpression in a variety of cancers and rare expression in healthy tissue, motivating expansion of interleukin 13 (IL13)–based chimeric antigen receptor (CAR) T cell therapy from glioblastoma into systemic malignancies." (PMID 35939683, 2022). "Binding of IL-13Rα1/IL-4Rα and IL-13 results in apoptosis escape in glioblastoma cells usually induced by signal transducer and STAT-6 pathways is considered another significant hypothesis in this case." (PMID 35612318, 2022). "It is obvious from literature that IL13α2R is promising target for chemotherapy cytotoxic drugs, i.e. to guide liposomes to the glioblastoma tumor site to cope with overexpressed IL13α2R receptors, doxorubicin loaded liposomes functionalized with IL-13 were fabricated and evaluated." (PMID 35612318, 2022). "More recently, the same group reported on a patient with recurrent multifocal glioblastoma from an ongoing phase I clinical trial with autologous CAR-T cells carrying an improved second-generation CAR with an IL-13 mutein and CD137 and CD3ζ signaling domains (NCT02208362, clinicaltrials.gov)." (PMID 31798595, 2019). "Interestingly, both IL-13 mutants showed the same proinvasive activity in colorectal cancer and glioblastoma cells than the wild-type IL-13." (PMID 30318506, 2018). "In glioblastoma cells, IL-13 efficiently promoted the invasion capacity." (PMID 30318506, 2018). "Furthermore, M(GM-CSF) were found to be more phagocytic than M(IL-4 + IL-13) towards primary human glioblastoma cells in the context of CD47 blockade ex vivo." (PMID 29084248, 2017). "Less is known about the role of IL-13 in glioblastoma biology." (PMID 25464980, 2014). "As an example, treatment with doxorubicin encapsulated in interleukin-13 (IL-13)-conjugated liposomes resulted in improved survival and enhanced tumor reduction in an intracranial model of glioblastoma multiforme (GBM) as compared to unconjugated liposomes with the same doxorubicin concentration." (PMID 23650496, 2013). "For example, the creation of a novel IL13 variant, termed IL13 (4MS) engineered to enhance selectivity for the IL13Rα2 receptor over IL13Rα1, has been incorporated into a bispecific CAR-T design which aimed to improve the efficacy of CAR-T cell therapy against glioblastoma." (PMID 41601679, 2026). "For instance, compared to traditional 2D glioblastoma cultures, extracellular vesicles released by 3D tumor organoids displayed a higher abundance of miRNAs involved in immunoregulatory signaling, such as interleukin-4 (IL-4) and interleukin-13 (IL-13) cytokine pathways." (PMID 40806235, 2025). "Other cancer types associated with excessive IL-13 activity include pancreatic cancer; colorectal cancer (CRC); glioblastoma multiforme (GBM); renal cell carcinoma; mesothelioma; and malignant melanoma." (PMID 39000142, 2024).